SEMA4C (semaphorin 4C)
Description:
Cell surface receptor for PLXNB2 that plays an important role in cell-cell signaling. PLXNB2 binding promotes downstream activation of RHOA and phosphorylation of ERBB2 at 'Tyr-1248'. Required for normal brain development, axon guidance and cell migration (By similarity). Probable signaling receptor which may play a role in myogenic differentiation through activation of the stress-activated MAPK cascade.
Synonyms: SEMAI; Semacl1; Semaf; M-SEMA-F
Tractability: Antibody: UniProt predicts a signal peptide or a membrane-spanning region; its Gene Ontology location is reachable by antibodies, with medium confidence. PROTAC: ubiquitination databases record sites on it; its protein half-life has been measured.
Gene: Protein-coding gene on chromosome 2 (96,859,718 to 96,873,840, reverse strand). Ensembl gene ENSG00000168758.
Subcellular location: Postsynaptic density membrane; Cytoplasmic vesicle, secretory vesicle, synaptic vesicle membrane
Gene Ontology:
Molecular function: protein binding; chemorepellent activity; neuropilin binding; semaphorin receptor binding
Biological process: muscle cell differentiation; positive regulation of stress-activated MAPK cascade; axon guidance; cell migration in hindbrain; negative chemotaxis; neural crest cell migration; neural tube closure; positive regulation of cell migration; semaphorin-plexin signaling pathway; cerebellum development; regulation of postsynapse assembly
Cellular component: extracellular region; plasma membrane; postsynaptic density; synaptic vesicle membrane; glutamatergic synapse; postsynaptic density membrane
Genetic constraint (gnomAD): Loss-of-function variants: 19 observed, 91.51 expected, observed/expected ratio (o/e) 0.21, 90% interval 0.14 to 0.31. The upper end of that interval is the gene's LOEUF score, 0.31, which puts it in group 1 of 6, group 1 being the genes least tolerant of losing a copy. Missense variants: 811 observed, 1,132.4 expected, observed/expected ratio (o/e) 0.72, 90% interval 0.68 to 0.76. Synonymous variants: 428 observed, 490.83 expected, observed/expected ratio (o/e) 0.87, 90% interval 0.81 to 0.94.
Homologues: Orthologues: chimpanzee SEMA4C (99% identical), macaque SEMA4C (97% identical), pig SEMA4C (93% identical), dog SEMA4C (93% identical), guinea pig SEMA4C (90% identical), rabbit SEMA4C (89% identical), mouse Sema4c (88% identical), rat Sema4c (87% identical), tropical clawed frog sema4c (60% identical), zebrafish sema4c (56% identical). Paralogues in human: SEMA4G (38% identical), SEMA4B (35% identical), SEMA4D (35% identical), SEMA4F (31% identical), SEMA4A (30% identical), SEMA3A (28% identical), SEMA3B (28% identical), SEMA3D (27% identical), SEMA3F (26% identical), SEMA3E (26% identical), SEMA5B (26% identical), SEMA3G (26% identical), and 7 more.
Diseases named in the same sentence as SEMA4C in open-access papers:
SEMA4C is named in the same sentence as 35 diseases in open-access papers, as found by Europe PMC text mining. Sharing a sentence is not in itself a finding about the gene and the disease. The quoted sentences say what the papers report.
breast carcinoma (19 papers, 2015 to 2025). "For instance, semaphorin 4C (SEMA4C) has shown promising diagnostic potential for breast cancer, with elevated serum levels significantly associated with tumor presence and reduced levels postsurgery, suggesting its utility in monitoring disease progression." (PMID 41479846, 2025). "High expression of SEMA4C transcripts was associated with relative cancer aggression, as evidenced by shorter survival in an analysis of 1402 breast cancer patients from The Cancer Genome Atlas (TCGA) cohort." (PMID 37685898, 2023). "Overexpression of SEMA4C led to increased migration and invasion that was dependent on the downstream expression of Rho A, which has previously been associated with breast cancer metastasis." (PMID 37685898, 2023). "SEMA4C is also associated with resistance to commonly used breast cancer therapies." (PMID 37685898, 2023). "Thus, not only could membrane-bound Sema4C be a promising target to macrophage for immunotherapy, but soluble Sema4C could also be a diagnostic biomarker for breast cancer." (PMID 35155237, 2022). "Notably, increased Sema4C expression in breast cancer cells has also been associated with resistance to paclitaxel-based chemotherapy, while knocking-down its expression could partly recover drug sensitivity." (PMID 33537086, 2021). "Notably, soluble Sema4C can be released from the cell surface due to proteolytic cleavage by matrix metalloproteinases (MMPs), and it was proposed as promising serum marker for the early diagnosis and the assessment of metastasis risk in breast cancer." (PMID 33537086, 2021). "Thus, in addition to Sema4C, Sema7A could represent another potential therapeutic target and a predictive biomarker for ER+ breast cancer patients at high risk for resistance to hormonal therapy and metastatic relapse." (PMID 33537086, 2021). "Based on publicly available databases, we also found that high SEMA4C mRNA expression in breast cancer correlates with unfavorable DMFS and OS." (PMID 40818975, 2025). "To determine the functional importance of SEMA4C in tumor clustering, we knocked down SEMA4C in the breast cancer cells." (PMID 40818975, 2025). "Sema4C was found to promote the proliferation of breast cancer cells, and its expression in breast cancer is correlated with poor prognosis." (PMID 37627074, 2023). "Knock-down of either plexin-B2 or sema4C leads to cell cycle arrest, senescence, and cytokinesis defects in breast cancer-derived cells." (PMID 37627074, 2023). "Semaphorin 4C (SEMA4C) and its corresponding receptor, PlexinB2, are overexpressed in breast cancer tissue, with implications for both cancer progression and metastasis, as well as resistance to hormonal and chemotherapy." (PMID 37685898, 2023). "Sema4C, a transmembrane protein, is overexpressed in multiple types of malignant tumors, including breast cancer, esophageal cancer, gastric cancer, and rectal cancer." (PMID 35155237, 2022). "A multicenter retrospective study demonstrated that soluble Sema4C was a potential biomarker for breast cancer diagnosis." (PMID 35155237, 2022). "In breast cancer, the functions of Sema4C in macrophage recruitment contribute to tumor malignant properties." (PMID 35155237, 2022). "Elevated levels of the transmembrane semaphorin Sema4C have been correlated with poor outcome of breast cancer." (PMID 33537086, 2021). "For instance, it was demonstrated that Sema4C forward signaling (via its receptor PlexinB2) is specifically required for breast cancer cell growth." (PMID 33537086, 2021). "High expression of SEMA4C correlates with poor prognosis of cervical cancer, breast cancer, lung cancer and HCC patients." (PMID 33177246, 2020). "SEMA4C promotes oncogenic signaling in breast cancer, hepatocellular cancer, and osteosarcoma, it also regulates proliferation, migration, lymphangiogenesis, and metastasis of cancer cells." (PMID 33177246, 2020).
breast carcinoma (continued). "Previous studies have demonstrated that Sema4C is highly expressed in breast cancer and lung cancer cells and can prompt the invasion and metastasis of tumors by inducing EMT21,22." (PMID 31776419, 2019). "Taken together, these results indicated that Sema4C plays a critical role in regulating PR-induced EMT in breast cancer cells." (PMID 25605244, 2015). "In the current study, we observed that overexpression of miR-125b inhibited cell migration and invasion through targeting Sema4C in breast cancer cells." (PMID 25605244, 2015). "Future therapeutics aimed at blocking PLXNB2 and SEMA4C/4A interactions can potentially serve as targeting strategies in breast cancer, especially TNBC and complement existing treatments, such as pembrolizumab, Sacituzumab72,73, and Palbociclib74 for improved outcomes." (PMID 40818975, 2025). "High SEMA4C levels in breast cancer correlate with tumor progression and poor prognosis." (PMID 33177246, 2020). "For paclitaxel resistance, the following miRNAs are relevant, miR-17-5P for the target PTEN in ovarian cancer, miR-30c for the targets VIM, IL-11 in breast cancer, miR-125b for Sema4C and Bak1 in breast cancer, and miR-100 for mTOR, miR-145 for P-gp in ovarian cancer, and miR-181a for PTEN in NSCLC." (PMID 35582143, 2019). "Taken together, activation of miR-125b or inactivation of Sema4C may be a useful strategy to reverse chemotherapy resistance in breast cancer." (PMID 25605244, 2015). "Our results revealed that re-expression of miR-125b or inhibition of Sema4C could be potential therapeutic approaches for treating PR breast cancer." (PMID 25605244, 2015). "In addition, Sema4c was reported to promote angiogenesis in breast cancer." (PMID 35382569, 2022). "The newly identified role of PLXNB2 in CTC clustering in conjunction with its ligands SEMA4C in tumor cells and SEMA4A in monocytes promotes metastasis, and is correlated with lower OS and DMFS in the context of advanced breast cancer, TNBC in particular." (PMID 40818975, 2025). "In cervical cancer, miR-31-3p/SEMA4C signalling drives EMT and cisplatin resistance, adding weight to its involvement in endocrine and chemotherapy response in breast cancer." (PMID 37685898, 2023). "Therefore, this study aims to explore the effects of miR-138 targeting SEMA4C in BC cells on epithelial-mesenchymal transition and invasion, to verify the potential of miR-138 as a clinical BC tumor marker, and to provide molecular targeted therapy for breast cancer New reference path." (PMID 34747314, 2021). "Plenty of miRNA-mRNA axes, such as miR-34a-Notch1 axis, miR-125b-Sema4c axis, miR-181-Bcl-2 axis, and miR-27b/CBLB/GRB2 axis, were reported that regulated taxanes-resistance in breast cancer." (PMID 32974144, 2020). "Ectopic expression of miR-125b in breast cancers and lung cancers and of miR-25-3p in CC17 notably reversed the EMT phenotype and regulated PR- and CR-induced EMT by downregulating Sema4C expression." (PMID 31776419, 2019). "Sema4C with plexin-B2 receptor promotes macrophage infiltration in TME, and promotes tumor growth and progression by activating the NF-κB pathway to induce CSF-1 production in breast cancer." (PMID 35155237, 2022). "Moreover, SEMA4C overexpression promotes cellular proliferation, migration and epithelial-mesenchymal transition (EMT) in breast cancer and non-small cell lung cancer." (PMID 33177246, 2020). "Sema4C, the target of many miRNAs including miR-125b, miR-25-3p, miR-205, miR-138, and miR-31, is involved in the EMT-mediated chemotherapeutic resistance of many malignant tumors, including breast cancer, cervical cancer, HCC, and lung cancer." (PMID 31776419, 2019). "In our previous studies, tumor-associated lymphatic endothelial cells (LECs) were found for the first time to produce soluble Sema4C (sSema4C) through MMP cleavage, and increased serum sSema4C was detected in patients with breast cancer and cervical cancer and in those with metastasis." (PMID 31776419, 2019).
cervical cancer (6 papers, 2019 to 2025). A primary or metastatic malignant neoplasm involving the cervix. "In this study, high expression levels of Sema4C were more frequently found in cervical cancer tissues and were associated with poor prognosis, whereas miR-31-3p was significantly downregulated in cervical cancer tissues." (PMID 31776419, 2019). "Elevated Sema4C expression has been associated with poor prognosis in cervical cancer patients." (PMID 33537086, 2021). "High expression levels of Sema4C were more frequently found in cervical cancer tissues and were associated with poor prognosis, whereas miR-31-3p was significantly downregulated in cervical cancer tissues, which was associated with shorter disease-free and overall survival." (PMID 31776419, 2019). "Further proofs of the role of SEMA4C in cervical cancer can be derived from the studies of Jing L. and colleagues." (PMID 33803151, 2021). "The repression of miR-25-3p ensures high levels of SEMA4C in cisplatin resistant cervical cancer cells." (PMID 33803151, 2021). "In vitro, in various experimental cell models of cervical cancer, SEMA4C was able to potentiate tumor lymphangiogenesis and lymphatic metastasis, modulate TGFβ-mediated EMT and promote EMT-mediated cisplatin resistance." (PMID 32899940, 2020). "The results above suggest that Sema4C plays an important regulatory role in EMT in cervical cancer cells." (PMID 31776419, 2019). "The aim of this study was to explore the potential role of miR-31-3p/Sema4C in regulating EMT in cisplatin-resistant (CR) cervical cancer cells." (PMID 31776419, 2019). "MiR-31-3p was identified to directly target Sema4C and mediated the biological functions including drug resistance of Sema4C in cervical cancer cells." (PMID 31776419, 2019). "A CCK8 assay was used to detect cisplatin resistance in cervical cancer cells after treatment with Sema4C siRNA or miR-31-3p mimic." (PMID 31776419, 2019). "After 24 h of pretreatment with Sema4C si2 (25 nM) or miR-31-3p mimic (50 nM), the inhibitory effect of 5 μM cisplatin on the growth of cervical cancer cells was significantly enhanced compared with cisplatin alone." (PMID 31776419, 2019). "Therefore, it is of great theoretical and innovative significance to clarify the functional role and regulatory mechanism of Sema4C in cervical cancer cells." (PMID 31776419, 2019). "Overexpression of miR-31-3p or downregulation of Sema4C may be a new approach to reverse the resistance to chemotherapy in cervical cancer." (PMID 31776419, 2019). "Furthermore, miR-31-3p was identified to directly target Sema4C, and upregulation of miR-31-3p reversed EMT-mediated biological functions, including cisplatin resistance of Sema4C in cervical cancer cells." (PMID 31776419, 2019). "Thus, silencing Sema4C or overexpression of miR-31-3p could be a novel approach to treat drug resistance to chemotherapy in cervical cancers." (PMID 31776419, 2019). "Consistent with the high expression of Sema4C in cervical cancer cells and the highest expression in Caski cells, the candidate target miRNAs were detected to have low or no expression in cervical cancer cells and the lowest expression was in Caski cells." (PMID 31776419, 2019).
colorectal cancer (4 papers, 2014 to 2025). A primary or metastatic malignant neoplasm that affects the colon or rectum. "The transmembrane protein SEMA4C is overexpressed in several malignant tumors, including breast, esophageal, gastric, and colorectal cancers." (PMID 40103807, 2025). "Our findings indicate that SEMA4C plays an important role in colorectal cancer invasion and metastasis." (PMID 33177246, 2020). "Additionally, research on the biological role of SEMA4C in colorectal cancer remains limited." (PMID 40103807, 2025). "However, the roles and prognostic value of SEMA4C in colorectal cancer (CRC) remain unclear." (PMID 33177246, 2020). "However, the prognostic significance of SEMA4C in colorectal cancer is not known." (PMID 33177246, 2020).
non-small cell lung carcinoma (3 papers, 2019 to 2021). A group of at least three distinct histological types of lung cancer, including non-small cell squamous cell carcinoma, adenocarcinoma, and large cell carcinoma. "According to bioinformatics, it was found that miR-138 and SEMA4C have predicted binding sites, and studies have shown that miR-139 targeting SEMA4C can affect the epithelial-mesenchymal transition of non-small cell lung cancer cells." (PMID 34747314, 2021). "Moreover, SEMA4C knockdown inhibits the growth and EMT of non-small-cell lung cancer (NSCLC) cells." (PMID 33177246, 2020).
colon cancer (2 papers, 2020 to 2022). "The association between SEMA4C protein levels and the clinicopathological variables in the TMA cohort of colon cancer patients." (PMID 33177246, 2020). "Semaphorins (SEMAs) are membrane-bound or soluble proteins involved in organ development and cancer progression, and among the SEMAs differentially expressed in colon cancer tissues, patients with tumors with higher SEMA4C (Semaphorins-4C) expression have lower survival rates." (PMID 36505481, 2022). "Univariate and multivariate Cox regression analysis of the prognostic significance of SEMA4C protein expression and other clinicopathological parameters in the TMA cohort of colon cancer patients." (PMID 33177246, 2020).
esophageal cancer (2 papers, 2015 to 2020). A primary or metastatic malignant neoplasm involving the esophagus. "Oncomine database analysis showed that SEMA4C mRNA levels were significantly upregulated in colorectal, gastric, head and neck, esophageal cancers, and sarcoma compared to the corresponding normal tissues." (PMID 33177246, 2020). "Moreover, high expression of Sema4C has been observed in esophageal cancer, gastric cancer and rectal cancer and is correlated with lymphatic metastasis." (PMID 25605244, 2015).
glioblastoma (2 papers, 2015 to 2023). The most malignant astrocytic tumor (WHO grade IV). "Among the Sema4 genes, SEMA4B and SEMA4C showed mild expression increase in gliomas and glioblastoma subtypes, while the other Sema4s appeared mainly unchanged or downregulated." (PMID 25762646, 2015). "Plexin-B2 also transduces sema4C signals in glioblastoma cells." (PMID 37627074, 2023). "Activation of plexin-B2 with sema4C also acts synergistically with HGF-activated MET to promote MET phosphorylation and to promote the progression of glioblastoma." (PMID 37627074, 2023).
hepatocellular carcinoma (2 papers, 2020 to 2021). A malignant tumor that arises from hepatocytes. "SEMA4C is involved in oncogenic signaling and is a potential therapeutic target for invasive breast cancer, hepatocellular carcinoma, glioma and osteosarcoma." (PMID 33177246, 2020). "Another recent report demonstrated a tumor suppressive function of miR-642a in liver cancer (hepatocellular carcinoma (HCC)); miR-642a expression was decreased, which enabled increased SEMA4C expression and signaling via the p38 MAPK pathway." (PMID 34504167, 2021).
liver cancer (2 papers, 2021 to 2022). An epithelial or non-epithelial malignant neoplasm that arises from the liver. "Previous studies have shown that CYTOR can promote liver cancer progression through regulation of the miRNA-125a-5p/LASP1 axis and miR-125b/SEMA4C axis." (PMID 36452343, 2022).
Anxiety (1 paper, 2021). Intense feelings of nervousness, tension, or panic often arise in response to interpersonal stresses. "In contrast, both Sema4C−/− and PB2−/−, PB2-LOFRhoA mouse lines showed impairment of behaviors related to both auditory-cued fear memory and anxiety, suggesting a role for Sema4C acting via Plexin-B2 in inhibitory amygdaloid circuits." (PMID 31444474, 2021). "To further understand the role of Sema4C-Plexin-B2 signaling in the amygdala, we tested anxiety behavior using elevated plus maze (EPM) test, which is linked to amygdala function." (PMID 31444474, 2021). "It is also plausible that other brain regions not targeted in CaMK-PB2−/− mice (i.e., beyond the forebrain), but affected in the constitutive and global Sema4C−/− and PB2−/−, PB2-LOFRhoA mutants, come into play in regulating auditory-cued fear memory and anxiety." (PMID 31444474, 2021).
autoimmune disease (1 paper, 2022). A disorder resulting from loss of function or tissue destruction of an organ or multiple organs, arising from humoral or cellular immune responses of the individual to their own tissue constituents. "Among them, semaphorin 3A is important in downregulating autoimmune diseases, semaphorin 3E as a critical factor for protective immunity against intracellular chlamydia muridarum infection, and semaphorin 4C in protecting against allergic inflammation." (PMID 35734166, 2022).
colon adenocarcinoma (1 paper, 2020). "Next, we investigated the effects of SEMA4C silencing in the LoVo cells (metastatic human colon adenocarcinoma cell line)." (PMID 33177246, 2020).